INS (insulin)
Diseases named in the same sentence as INS in open-access papers (continued):
Sharing a sentence is not in itself a finding about the gene and the disease.
Hyperglycemia (continued). "Collectively, diabetes is closely linked with conditions that cause mTOR activation, namely, excessive caloric intake, even when preceding obesity, insulin resistance, and overt hyperglycemia development." (PMID 30510618, 2018). "Sulfonylureas, such as glimepiride, are widely used in human diabetic patients to stimulate insulin secretion from pancreatic beta cells and subsequently reduce hyperglycemia." (PMID 30510962, 2018). "Significance: A strong relationship between hyperglycemia, impaired insulin pathway, and cardiovascular disease in type 2 diabetes (T2D) is linked to oxidative stress and inflammation." (PMID 28891325, 2018). "Alleviation of hyperglycemia by administration of exogenous insulin is accompanied in about 60% of patients by a rapid reduction of daily insulin requirements (DIR) for maintenance of normal glycemia and HbA1C levels." (PMID 29568778, 2018). "The effort of the experimentations lead to the production of a delayed-acting insulin to counteract both hyperglycaemia and hypoglycaemia." (PMID 30405529, 2018). "In type 1 diabetes, insulin secretion is virtually absent, while glucagon secretion from the α–cell is still preserved, which removes the insulin-dependent pathways lowering BG levels and therefore BG can only go up, leading to hyperglycemia." (PMID 32232090, 2018). "DM is a noncommunicable disease in which there is a metabolic disorder of various etiologies described by sustained hyperglycemia with disorders of carbohydrate, fat, and protein metabolism following defects in insulin secretion, insulin action, or both." (PMID 30532775, 2018). "The basis for the variations in hyperglycemia and insulin use according to the type of surgical service requires further investigation to ensure that a unified treatment strategy is applied to all surgical patients." (PMID 29255628, 2018). "The first is considered to be responsible for >75% of insulin-induced glucose disposal from blood under either euglycemia or hyperglycemia, while the second is the organ enabling de-novo glucose production." (PMID 29768504, 2018). "They tend to have early pancreatic beta-cell dysfunction and early reduction of the insulin secretion peak, leading to more severe postprandial hyperglycemia, which is made even more serious by the traditional Chinese high-carbohydrate diet." (PMID 29476413, 2018). "Data from the present study suggest that basal insulin plus OHA therapy rapidly corrects hyperglycemia and also confers β-cell function benefits, possibly by eliminating glucotoxicity and providing a β-cell rest period." (PMID 30420969, 2018). "OA also attenuates fructose-induced hyperglycaemia by modulating enzymes involved in carbohydrate digestion, insulin secretion and insulin signalling." (PMID 30479649, 2018). "Protocol adherence will be measured and reported, and serious adverse events (rates of hyperglycaemia requiring new insulin; falls during mobilisation) will be collected and reported." (PMID 29402313, 2018). "A modulation of glucose metabolism as well as a more effective reduction of hyperglycemia, increase in insulin/glucose ratio and improvement of islet architecture and β-cells function was observed compared to standard red ginseng." (PMID 29300317, 2018). "Defects in insulin secretion, insulin action, or both, result in hyperglycemia, which when sustained over extended periods of time, results in damage, dysfunction and eventually failure of various organs." (PMID 29351335, 2018). "In this study, we showed efficacy in protecting diabetic mice from hyperglycemia for more than 10 d with a single dose of NPs (600 μg plasmid insulin (pINS)) delivered orally." (PMID 30128227, 2018). "Characteristics of insulin-resistant phenotype include impaired glucose metabolism or tolerance, elevated fasting glucose levels and/or hyperglycemia, and decreased insulin-mediated glucose reductions in the suppression of glucose production inside the body." (PMID 30425746, 2018).
Hyperglycemia (continued). "The consumption of sugars will stimulate an increase in amylase and insulin production and in so doing postprandial hyperglycemia will be downregulated." (PMID 30293998, 2018). "Our findings are also in accordance with a recent study which found that the current basal-bolus insulin regimens were inadequate for controlling hyperglycemia in inpatients receiving prednisolone ≥10 mg/d." (PMID 30373567, 2018). "While treating hyperglycemia with insulin reduces morbidity and mortality, it increases glycemic variability and hypoglycemia risk, both of which have been associated with an increase in mortality." (PMID 29631990, 2018). "SMBG is especially important for insulin-treated patients to monitor and prevent asymptomatic hypoglycemia and hyperglycemia." (PMID 29527102, 2018). "Here, we show the existence of a prediabetic state in Ambra1 mice, characterized by hyperglycemia, intolerance to glucose and insulin resistance." (PMID 30532260, 2018). "This increase in insulin signaling, plus hyperglycemia, though, leads to an increase in free fatty acids by inappropriate lipolysis and the generation of insulin resistance, particularly in the fat body." (PMID 29854726, 2018). "Pre-treatment of diabetic rats with vildagliptin significantly reduced hyperglycaemia (p<0.001) and increased plasma insulin level (p<0.001) and decreased HOMA1-IR index (p<0.05) comparing to the diabetic group." (PMID 30023334, 2018). "Failure or insufficiency of insulin secretion from pancreatic beta‐cells increases glucose and free fatty acid level in circulation and subsequently contributes to the emergence of hyperglycaemia and dyslipidaemia." (PMID 29516672, 2018). "ATM also stimulates inflammatory cytokines that inhibit insulin signaling and expedites hepatic gluconeogenesis, and postprandial hyperglycemia." (PMID 30170598, 2018). "DM is a chronic disease characterized by hyperglycemia from defects in insulin secretion, insulin action, or both." (PMID 29619381, 2018). "In total, 6 patients had documented hypoglycaemia (BGL < 4.0 mmol/L) of whom all were on either insulin or sulphonylurea, and 35 experienced hyperglycaemia (BGL ≥ 14 mmol/L) during their hospital admission." (PMID 30564287, 2018). "Type 1 diabetes (T1D) is caused by an autoimmune attack on the β-cells of the pancreas, which lead to pancreatic islet inflammation (insulitis), β-cell apoptosis and subsequent hyperglycemia due to low insulin production." (PMID 30294283, 2018). "In healthy subjects, hypo- and hyperglycemia are counteracted by a physiological control system that includes pancreatic hormones such as insulin, glucagon, and amylin." (PMID 29547553, 2018). "It is a condition characterized by chronic hyperglycemia resulting from defects in insulin secretion, insulin action, or both." (PMID 29986694, 2018). "N-Acetylcysteine as an antioxidant and precursor of glutathione was described to control hyperglycemia and to modulate insulin action and secretion." (PMID 29675131, 2018). "The prevention of long-term hyperglycemia and rapid implementation of intensive insulin therapy certainly reduce the prevalence of early diabetic cataract in children and adolescents." (PMID 29755521, 2018). "Nevertheless, the effect of regimen 9 (sdpBD-CAM800), which includes Dex, was equal to regimen 11 (sdpBRMd-CAM800), but the former was discontinued because of severe hyperglycemia which required insulin therapy." (PMID 29454372, 2018). "In these tissues, facilitated diffusion of glucose occurs in an insulin-independent manner via the glucose transporter 1 (GLUT1) with the resultant intracellular hyperglycaemia possibly a key initiating factor in the development of diabetic complications." (PMID 30210450, 2018). "The current medications, insulin and anti-diabetic drugs, can transiently decrease the hyperglycemia in diabetic patients and rather represent ameliorative treatment than cure." (PMID 30386256, 2018).
Hyperglycemia (continued). "The most severe hyperglycaemia in ob/ob mice occurs at the age of 3–5 months, and the severity decreases thereafter; islet volume in the pancreas is increased, and insulin secretion is maintained." (PMID 30599002, 2018). "DM is a chronic metabolic disease that results from defects in insulin action, insulin secretion, or both, leading to persistent hyperglycemia." (PMID 30558294, 2018). "As with predictors of hyperglycemia, these data can be used to refine the treatment algorithms used to assist with decision making in situations when basal-bolus insulin therapy would be appropriate." (PMID 29255628, 2018). "In human islets exposed to continuous hyperglycaemia the use of diazoxide to inhibit insulin secretion helps to prevent hyperglycaemia-induced damage to the islets, and preserves their capacity to synthesise and release insulin." (PMID 30200572, 2018). "In most East African countries, insulin (between once and three times daily) is the treatment of choice to control hyperglycemia in GDM." (PMID 29508275, 2018). "STZ-induced DM rats served as hyperglycemia interconnected with the downregulation and discharge of insulin secretion." (PMID 35542112, 2018). "Postprandial hyperglycemia and insulin sensitivity differ among lean young adults of different ethnicities." (PMID 29527102, 2018). "Hyperglycemia is one of the most prevalent metabolic derangements in sepsis patients, presumably resulting from altered glycogen metabolism and profound insulin resistance." (PMID 29976786, 2018). "In a multiple intravenous MSC treatment in STZ-induced T2DM rats, a controlled hyperglycemia with enhanced serum insulin and C-peptide was found at 9 weeks." (PMID 30046616, 2018). "Current standards for treating noncritically ill inpatients encourage implementing basal-bolus insulin therapy for hyperglycemia to achieve the recommended glucose targets." (PMID 29255628, 2018). "SeP serves as a hepatokine that contributes to the onset of hyperglycemia in type 2 diabetes by imparting insulin signal transduction in the liver and skeletal muscle." (PMID 29547524, 2018). "As a compensatory response to postprandial hyperglycemia, plasma insulin concentration rises to maintain normal glucose homeostasis by inducing glucose uptake in the skeletal muscle and liver while simultaneously inhibiting hepatic glucose production." (PMID 29484304, 2018). "In normal condition insulin and hyperglycemia promotes glucose disposal through suppression of hepatic glucose production, stimulation of glucose uptake by liver and peripheral tissues." (PMID 30072892, 2018). "Previous studies indicated that insulin ameliorates the activity and expression of hepatic PK, leading to ameliorated hyperglycemia in alloxan monohydrate-treated rats." (PMID 29342975, 2018). "Both extremely premature human neonates and extremely premature baboon neonates exhibit postnatal insulin resistance, contributing to the development of hyperglycemia and its related morbidities." (PMID 30540820, 2018). "Findings suggest that hyperglycemia also happens due to the inhibitory effect of amylin hormone on glucose-exciting insulin formation, which at last enhances gluconeogenesis." (PMID 29805204, 2018). "NOD mice normally spontaneously develop hyperglycemia, between 12 and 30 weeks of age due to autoimmune destruction of the insulin secreting β-islet cells within the pancreas." (PMID 29707204, 2018). "We further analyzed how therapy was administered with respect to hyperglycemia after observing that less basal-bolus insulin therapy was administered in the neurosurgical, orthopedic and urologic services compared with general surgery." (PMID 29255628, 2018). "Skeletal muscle is the primary site for insulin-dependent glucose uptake, and along with the liver, plays an important role in the development of insulin resistance (IR) and hyperglycaemia during states of metabolic stress." (PMID 29129636, 2018).
Hyperglycemia (continued). "Treatment of hyperglycemia, predominantly involving insulin therapy, remains controversial in the critically ill." (PMID 29631990, 2018). "The observed hyperglycemia following pasireotide treatment is due to the suppression of insulin and incretin response (glucagon-like peptide 1 and glucose-dependent insulinotropic polypeptide)." (PMID 29313180, 2018). "Treatment of inpatient hyperglycemia is usually with basal bolus insulin in a dose calculated by the patient’s weight, with lower doses recommended in patients who are at a higher risk for hypoglycemia." (PMID 29688879, 2018). "Activation of the hepatic cannabinoid type 1 receptor (CB1R) induces insulin resistance and gluconeogenesis via endoplasmic reticulum (ER) stress, thereby contributing to hyperglycemia." (PMID 29570673, 2018). "Fasting hyperglycemia was present in all groups at study termination, indicating disturbances in glucose metabolism, even though fasting insulin levels remained similar between groups." (PMID 29410708, 2018). "Hyperglycemia, hyperplasia and hypertrophy stimulate the fetal beta cells, leading to increased insulin secretion and high levels of insulin in the blood." (PMID 30820209, 2018). "The C allele of rs780094 was associated with lower lactate levels in fasting but increased lactate level during hyperglycemia independently of insulin levels." (PMID 30375486, 2018). "Treatment of Akita mice with insulin implants for 20 weeks normalized hyperglycemia and decreased urinary albumin excretion." (PMID 29641741, 2018). "Toachieve rapid control in the hospitalized patient with hyperglycemia(persistent glycemia > 180 mg/dL for a period > 12 hours prior tosurgery), insulin therapy should be used either by continuous rapidintravenous or subcutaneous infusion." (PMID 30652752, 2018). "For example, several groups including my own have found that in vitro exposure of differentiated skeletal muscle cells (myotubes) to prolonged (>24-h) hyperglycemia reduces insulin-stimulated glucose uptake." (PMID 30061841, 2018). "Type 1 diabetes (T1D) is an autoimmune disease characterized by pancreatic insulin-producing cells, which results in hyperglycemia." (PMID 30202421, 2018). "DM is a chronic disease diagnosed by hyperglycemia, owing to insufficient insulin production or inadequate cellular sensitivity to insulin, and progressive decline in B-cell function." (PMID 30564116, 2018). "A trend towards a reduction in the expression of insulin was revealed in malaria with hyperglycaemia." (PMID 29993021, 2018). "Its primary pathomechanism is persistent hyperglycemia, due to inability of a subject’s cells to induce adequate metabolic responses to insulin produced by pancreatic β islet cells." (PMID 29518003, 2018). "Streptozotocin is known to destroy insulin-producing pancreatic beta cells, thereby leading to hypoinsulinemia and hyperglycemia in exposed animals." (PMID 30050652, 2018). "The antidiabetic drug glibenclamide used in this study as a positive control reduces the postprandial hyperglycemia by increasing insulin secretion from β cell." (PMID 30285723, 2018). "Her treatment course was complicated by hyperglycemia necessitating insulin therapy, but after 3 months of therapy, she reported improvement in her dyspnea, and repeat imaging revealed a significant decrease in the size of the lung mass and lymphadenopathy." (PMID 29650028, 2018). "Antenatal exposure to BTM at 600 μg/kg/d led to hyperglycemia, glucose intolerance and low capacity of insulin secretion in the 16-week-old offspring." (PMID 30212527, 2018). "In perfect agreement with our results, insulin infusion to control hyperglycemia in experimental sepsis, increased glutathione content in the liver by 78%." (PMID 29300728, 2018). "Hyperglycemia is common in internal medicine units, and the recommended treatment is basal bolus insulin." (PMID 29688879, 2018).
Hyperglycemia (continued). "The mechanism of action of metformin comprises suppression of hepatic gluconeogenesis and increasing insulin sensitivity, which mitigates hyperglycaemia." (PMID 29522471, 2018). "The impaired function of the glucokinase enzyme in both the pancreas and in the liver results in hyperglycemia and insulin resistance." (PMID 29760458, 2018). "Despite the lack of a genotype effect with exercise in protecting against olanzapine-induced hyperglycemia there were differences between WT and IL-6−/− mice with regards to serum insulin concentrations." (PMID 29335597, 2018). "Eventually, the β-cells fail to sustain a sufficient insulin production resulting in hyperglycemia and T2D." (PMID 30248999, 2018). "Banting and Best had obtained, indeed short-acting insulin preparations, lasting about 6 h, with inevitable and subsequent peaks of hyperglycaemia and glycosuria, within 24 h." (PMID 30405529, 2018). "Of note, any defect in insulin regulation in blood triggers the in metabolic disorders of carbohydrate, fat, and protein leading to a condition of hyperglycemia." (PMID 30046616, 2018). "Recently, several reports presented that hESC/iPSC-derived cells enriched with specific transcription factors can form glucose-responsive insulin-secreting cells in vitro and transplantation of these cells ameliorates hyperglycemia in diabetic mice." (PMID 30594258, 2018). "Diagnostic work-up revealed hyperglycemia with severe ketoacidosis (glucose: 907mg/dL, blood gas pH: 6.84, HCO3: 6 mmol/L), that was managed with intravenous (IV) fluids and IV insulin administration." (PMID 28943514, 2018). "A single dose of orally administered NPs (600 μg plasmid insulin (pINS)) to diabetic mice can protect the animals from hyperglycemia for more than 10 d." (PMID 30128227, 2018). "In contrast, responding to a predictive alarm can result in eating carbohydrates even though the insulin pump is suspended, with resultant hyperglycaemia." (PMID 29423581, 2018). "Further prospective, randomized controlled research should focus on the risks and benefits of glycemic control via decreased glucose infusion rates and/or insulin infusion, and assess the relationship between hyperglycemia and cardiac adverse outcomes." (PMID 29419661, 2018). "A combination of relative hypoinsulinism, peripheral insulin resistance, and glucose infusion for nutrition is responsible for hyperglycemia." (PMID 29544513, 2018). "Patients must respond to feedback on hypoglycemia and hyperglycemia, adhere to lifestyle and treatment, and receive insulin adjustment under provider guidance." (PMID 30291085, 2018). "The exact mechanism of the insulin-induced hyperglycemia observed in our experimental model is yet to be investigated." (PMID 30400826, 2018). "The primary mechanism by which MSCs ameliorate hyperglycemia was considered to be their potential to differentiate into insulin producing cells (IPCs), and a number of modified protocols have been applied to improve their differentiation efficacy." (PMID 29988034, 2018). "Type 1 diabetes was induced with alloxan, and the animals presented hyperglycemia and reduction in insulin and body weight." (PMID 30622608, 2018). "Apart from decreasing insulin secretion, smoking impaired the accumulation of hepatic glycogen, thereby contributing to the development of hyperglycemia." (PMID 29437243, 2018). "Insulin and hyperglycemia play key roles in distinct phases of disease progression, via different mechanisms and differentially affecting the three major cell types: SMCs, macrophages and ECs." (PMID 30618774, 2018). "Under hyperinsulinemia, insulin-mediated glucose uptake in skeletal muscle accounts for approximately 75% and 95% of whole body basal glucose disposal at euglycaemia and hyperglycaemia respectively." (PMID 30199540, 2018). "Effect of galangin on plasma glucose and insulin levels in rats with streptozotocin-induced hyperglycaemia." (PMID 29952676, 2018).